BCL2 (BCL2 apoptosis regulator)
Diseases named in the same sentence as BCL2 in open-access papers (continued):
Sharing a sentence is not in itself a finding about the gene and the disease.
cancer (continued). "Over-production of Bcl-2/Bcl-xL-related proteins in cancer cells confers resistance to multiple chemotherapeutic agents whose mode of action is to trigger apoptosis." (PMID 24367419, 2013). "Cancer cells more resistant to hypoxia show that low O2 tension induces apoptosis as well as necrosis and completely prevents apoptosis by Bcl-2 and Bcl-X." (PMID 23314174, 2013). "The small-molecule inhibitors that block the anti-apoptotic function of Bcl-2 or Bcl-xL leading to recurrence of apoptosis in cancer cells have been proposed as potential new anti-cancer agents." (PMID 24050266, 2013). "Epigallocatechin gallate an important cancer chemopreventative agent of green tea has been shown to upregulate miR-16 with subsequent down-regulation of Bcl-2 in hepatocarcinoma cells." (PMID 23675407, 2013). "Further, it has been reported that knockdown or downregulation of Sp1, Sp3, and Sp4 represses expression of Sp-regulated genes, including VEGF and BCL-2, inhibits cancer cell growth, and induces apoptosis." (PMID 23626851, 2013). "In our present study we showed that inhibition of TNKS1 with XAV939 reduced Bcl-2 proteins in SH-SY5Y cancer cells consistent with the promotion of apoptosis." (PMID 24308762, 2013). "In contrast, cancer cells expressing high levels of IP3R2 will be addicted to high levels of Bcl-2 to suppress the pro-apoptotic activity of the hypersensitive IP3R2 in response to ongoing IP3 signaling." (PMID 23681227, 2013). "For instance, higher Bcl-2 to Bax ratios are commonly found in cancers, which not only confers a survival advantage to the cancer cells but also causes resistance to chemotherapies." (PMID 23800091, 2013). "Elevation of Bcl-2 protein expression contributes not only to the development of cancer but also to resistance against a wide variety of anti-cancer agents." (PMID 24339958, 2013). "In other studies, SAHA (vorinostat) reduced the pY705-STAT3, and the inhibition of pY705-STAT3 suppressed the Bcl-2 expression and enhanced the cytotoxicity of chemotherapeutic drugs to induce apoptosis in human cancer cell lines." (PMID 24278362, 2013). "Additional mechanisms have also been described that can cause cancer cells to become insensitive to ABT-263 treatment, such as loss of the pro-apoptotic BCL2 proteins, BAK or BIM." (PMID 23342165, 2013). "In particular, cancer cells expressing high levels of IP3R2 are addicted to IP3R/Bcl-2 complex formation and disruption of these complexes using peptide tools results in pro-apoptotic Ca2+ signaling and cell death." (PMID 23681227, 2013). "The expected advantage of targeting of both the Bcl-2 and Mcl-1 mechanisms of apoptosis resistance was demonstrated in various types of cancers." (PMID 23483560, 2013). "Bcl-2 is a critical apoptosis inhibitor with established carcinogenic potential, and can confer cancer cell resistance to therapeutic treatments by activating anti-apoptotic cellular defense." (PMID 23977251, 2013). "Levels of staining of Cyclin D1 and Bcl-2 in TSCC cancer tissues were inversely correlated with miR-195 levels." (PMID 23451060, 2013). "The pro-apoptotic BAX, BAK and BAD genes are believed to oppose cell carcinogenesis, while the BCL2 gene can promote cancer cell growth by blocking apoptosis." (PMID 23637776, 2013). "Overexpression of antiapoptotic BCL-2 proteins has long been shown to correlate with resistance to chemotherapy and radiotherapy in various cancers." (PMID 23840208, 2013). "This would expand the pool of free pro-apoptotic effectors and, thus, induce apoptosis in cancer cells in which overexpressed Bcl-2, Bcl-xL, or Mcl-1 provide survival cues." (PMID 23680104, 2013). "Cassia tora L. significantly induced apoptosis in cancer cells (P<0.05) by upregulating Bax, caspase-3 and caspase-9, and by downregulating Bcl-2." (PMID 23426077, 2013).
cancer (continued). "Our work demonstrates that DSW increased TRAIL-induced apoptosis, which can sensitize several cancer cells, by the result that Bcl-2 expression level was significantly decreased in the presence of the DSW extracts." (PMID 23743830, 2013). "Previous studies have shown that miR-195 prevents cell proliferation and promotes apoptosis in diverse cancers by binding to the 3′-UTRs of mRNAs of Bcl-2 and Cyclin D1." (PMID 23451060, 2013). "In many pathological studies, an unbalanced BCL2/BAX ratio (BCL2/BAX > 1) has been recognized as a signature of the acquisition of apoptosis resistance in cancer cells." (PMID 24459422, 2013). "Another important modulator of the redox status in cancer cells is B-cell lymphoma-2 (Bcl-2) protein that is, overexpressed in a variety of cancer cells." (PMID 23762063, 2013). "Inhibition of the anti-apoptotic protein BCL-2 sensitizes cancer cells to chemotherapy induced apoptosis." (PMID 23847761, 2013). "Bcl-2 expression at low levels is required for cell survival; however, upregulation of the Bcl-2 gene can lead to formation of many common cancers and has been reported to play a role in resistance to conventional cancer treatments." (PMID 23977303, 2013). "Overexpression of Bcl-2 protein is common in many human cancers, and contributes to resistance to chemotherapy." (PMID 24161202, 2013). "GIAMP5/IAN5 interacts with Bcl-2 and Bcl-XL and inhibits apoptosis during T-cell development and is highly expressed in human B-cell lymphoid malignancies." (PMID 23431463, 2013). "Particularly, necroptosis is able to overcome resistance to cancer drugs mediated by P-glycoprotein, Bcl-2, and Bcl-xL in cancer cell lines." (PMID 23840441, 2013). "At that time, several mRNA targets of miR-148a such as DNA methyltransferase 3 beta (DNMT3B), DNA methyltransferase 1 (DNMT1), BCL2 were described in various cancers using transient transfection and Western blot analysis." (PMID 23383211, 2013). "Due to their central function in the apoptotic machinery, Bcl-2 proteins are often deregulated in the sense of a pro-survival effect, in cancer." (PMID 23441221, 2013). "Antiapoptotic Bcl-2 proteins such as Bcl-2, Bcl-XL, and Mcl-1 are often overexpressed in human cancers including childhood malignancies." (PMID 23420072, 2013). "Colony forming efficiency, a reliable indicator of rapid in vitro growth and colony forming characteristic of cancer cells, also showed reduction in Bcl-2/Bcl-xL overexpressing cells and was consistent with induction of senescence in these cells." (PMID 24050266, 2013). "The expression level of bcl-2 differs between various cell types, however high levels and aberrant patterns of bcl-2 expression have been reported in a wide variety of human cancers." (PMID 24339958, 2013). "Other studies show both enhanced Ras and Bcl-2 protein expressions or elevated amounts of Bcl-2 mRNA in cancer cells upon drug treatment." (PMID 24216995, 2013). "A putative PPAR response element (PPRE) has been reported in the 3′-untranslated region of the Bcl-2 gene in human cancer cells." (PMID 23372817, 2013). "A good many studies have cumulatively proven that anti-apoptotic Bcl-2 members are attractive targets for anti-cancer therapy." (PMID 23705845, 2013). "The Bax/Bcl-2 ratios in all the carcinoma cells examined were less than 0.4, and were significantly lower than that of the HaCaT cells (p<0.01)." (PMID 24278362, 2013). "Since those early days a bulk of data have proven the role of Bcl-2 alterations in development of cancer including a number of animal models." (PMID 22683550, 2012). "Extract of M. charantia was reported to inhibit growth of several cancer cells by augmenting Bax/Bcl-2, Bad/Bcl-2, or Bak/Bcl-2." (PMID 23091557, 2012).
cancer (continued). "Accordingly, anti-Bcl-2 strategies have been widely developed as novel cancer therapy for various malignancies." (PMID 22666341, 2012). "The downregulation of Bcl-xL has been shown to induce apoptosis and increase chemosensitivity but resistance to chemotherapy is still observed in some cancer cells even after Bcl-2/Bcl-xL inhibition." (PMID 23171055, 2012). "Anti-apoptotic proteins, such as Bcl-2 and Bcl-xL, play an important role in the radioresistance of cancer cells." (PMID 23259599, 2012). "The degree of apoptosis was shown to correlate with the levels of the expression of Bcl-2, main antiapoptotic protein, and its overexpression in cancer cells ensures their resistance to chemotherapy." (PMID 23251109, 2012). "The percentage of biliary cancer cells showing high Bcl-2 expression (above grade 2+) was much lower; it was less than 1% of the counted cancer cells in all of the ChCs examined." (PMID 22654601, 2012). "High Bcl-2 expression has been correlated with poor clinical prognosis in cancer patients as well as resistance to conventional chemotherapeutic drugs." (PMID 23226540, 2012). "Previous studies have shown that blocking uPAR in various cancer cells reduced the expression of Bcl-2 and enhances the expression of Bax." (PMID 22984561, 2012). "The anti-apoptotic oncoprotein Bcl-2 has been shown in a number of studies to confer cancer-cell resistance to IR and chemotherapy." (PMID 22952453, 2012). "Previous studies by RNA interference (RNAi) show that both survivin and bcl-2 are regulated by Sp1, Sp3 and Sp4 in cancer cells." (PMID 23110215, 2012). "In cancer, the balance between Bcl-2-negative regulators (Bcl-2/Bcl-xL/Mcl-1/A1/BCL-w) and positive regulators (Bax/Bak/BH3-only proteins) are disturbed such that initiation of apoptosis is difficult to achieve." (PMID 22240779, 2012). "Improving our ability to stratify patients for treatment by developing more robust predictive biomarkers would promote the success of BCL-2 inhibitors in clinical trials and guide their future use in cancer therapy." (PMID 22880001, 2012). "Studies involving several hematological and solid malignancies have identified a correlation between intense Bcl-2 or Bcl-XL expression and poor patient response to cancer therapy and overall prognosis." (PMID 22654601, 2012). "This is the first study to show that ABT-737 down regulated the expression of Bcl-2 and Bcl-xL in cancer cells in a time-dependent manner." (PMID 23259599, 2012). "Beside inhibiting mitosis, DOCT induces phosphorylation of Bcl-2, which lead to apoptosis of cancer cells." (PMID 23493035, 2012). "Overexpression of BCL-2 by cancer cells promotes survival during tumorigenesis and can lead to acquired chemoresistance." (PMID 22880001, 2012). "IL-24-siRNA completely blocks Bcl-2 ubiquitination via reversion of Bcl-2 S-denitrosylation and protects it from proteasomal degradation which confirmed the significant role of MDA-7/IL-24 in regulating posttranslational modification of Bcl-2 in cancer cells." (PMID 22629368, 2012). "MDA-7/IL-24 was involved in the specific cancer apoptosis through suppression of Bcl-2 expression, which is a key apoptosis regulatory protein of the mitochondrial death pathway." (PMID 22629368, 2012). "Our present data clearly demonstrate that the overexpression of Mcl-1 in coordination with Bcl-2/Bcl-xL expression protects cancer cells from apoptosis." (PMID 23171055, 2012). "ABT-737, a rationally designed small molecule binds with high affinity to Bcl-2 and Bcl-xL, thereby antagonizing their anti-apoptotic functions and inducing apoptosis in many types of cancer cell." (PMID 23259599, 2012).
cancer (continued). "Many cancers exhibit a primed phenotype, including some that are resistant to conventional chemotherapy due to high BCL-2 expression." (PMID 22880001, 2012). "Reverse-transcription PCR and western blot were performed to detect the expression of Bcl-2 and Bcl-xL in the cancer cell lines." (PMID 23259599, 2012). "Specifically, HK, Bcl2, Bcl-xL, actin, and tubulin were found to interact with VDAC1 and alter its channel conductance (see VDAC1 Association with Proteins and Cancer)." (PMID 23233904, 2012). "In the last decade, new members of BCL2 gene family were discovered and cloned and were found to be differentially expressed in many types of cancer." (PMID 21941553, 2012). "Several reports had demonstrated the effectiveness of gossypol in targeting cancer cells with high level of Bcl-2 and its family members, by increasing cellular apoptosis when used as a single agent or in combination with gemcitabine." (PMID 23226540, 2012). "Our study demonstrated that in 10 cell lines derived from different cancers, high Bcl-2 baseline expression was observed in cell lines that were resistant to gemcitabine (GEM-R)." (PMID 23226540, 2012). "In mammalian cells, the Bcl-2 gene family contains a number of antiapoptotic proteins, including Bcl-2 and Bcl-xL, which is thought to be involved in resistance to conventional cancer treatment." (PMID 22701509, 2012). "Since the Bcl-2/Bax ratio and the Bcl-XL/Bax ratio has been shown to associate with survival outcomes in OSCC and other cancers, we examined if a similar association existed in our OSCC cohort using automated quantitative IHC analysis." (PMID 22852863, 2012). "Three of the targets—clusterin, survivin, Bcl-2—have well-characterized roles in mechanisms which protect cancer cells from apoptosis induced by cytotoxic drugs." (PMID 22989709, 2012). "ABT-737 is a rationally designed small molecule that binds with high affinity to Bcl-2 and Bcl-xL and antagonizes their anti-apoptotic function, thereby inducing apoptosis in many cancer cell types." (PMID 23259599, 2012). "Since NO played a crucial role in Bcl-2 denitrosylation and ubiquitination in cancer cell apoptosis induced by ZD55-IL-24, it suggested that Bcl-2 denitrosylation was a different mechanism from dephosphorylation induced by ROS." (PMID 22629368, 2012). "One mechanism by which cancer cells escape apoptosis is the overexpression of antiapoptotic genes, particularly of BCL2, Bcl-xL, XIAP and survivin." (PMID 22797576, 2012). "Bcl-xL and Bcl-2 which have anti-apoptotic function by protecting mitochondria from cytochrome c release are commonly over-expressed in cancers." (PMID 22389672, 2012). "Induction of apoptosis by down-regulation of anti-apoptotic gene bcl 2 and NFκB bcl-2 is the prominent member of a family of proteins that are responsible for deregulation of apoptosis and prevention of death in cancer cells." (PMID 22470431, 2012). "VDAC also serves as an anchor point for mitochondria-interacting proteins, some of which are also highly expressed in many cancers, such as hexokinase (HK), Bcl2, and Bcl-xL." (PMID 23233904, 2012). "The apoptogenic protein, Bax, was increased, whereas Bcl-2 was decreased after treating for 24 h in all cancer cells, indicating the involvement of mitochondrial pathway in MCME-induced cell death." (PMID 23091557, 2012). "Of the Bcl-2 family, Bcl-2 is a prototypic anti-apoptotic protein that is frequently overexpressed in several types of human cancers." (PMID 23251606, 2012). "Stat3 activation within these cancer tissues and cells leads to an in increased level of anti-apoptotic proteins including Bcl-2 and Survivin." (PMID 22879872, 2012).
cancer (continued). "In a reported study, bcl-2 has showed higher expression in benign and borderline tumors than malignant tumors." (PMID 22995373, 2012). "HS-1793 was also noted to display stronger antitumor effects than resveratrol in most cancer cells, to overcome the resistance conferred by Bcl-2 in U937 cells via 14-3-3, and to exert its antitumor activity via Bad." (PMID 22940714, 2012). "The constitutive activation of NF-κB promotes the more invasive phenotype of ER-negative cancer cells via induction of anti-apoptotic and pro-metastatic genes, such as Bcl-2 and granulocyte macrophage-colony stimulating factor (GM-CSF)." (PMID 22701533, 2012). "Our present study determined the significant role of Bcl-2 denitrosylation in its ubiquitin proteasome degradation, which finally mediates the caspase signal pathway activation and cancer cell apoptosis in response to ZD55-IL-24." (PMID 22629368, 2012). "TQ-induced increases in Bax/Bcl-2 ratio were also reported in other cancer cells, including MCF7, HL-60 and HCT116 cells." (PMID 23077516, 2012). "In conclusion, these studies indicate that statins are able to induce apoptosis in different cancer cell lines and the mechanism at the basis of induction of this important process involves the regulation of Bax and BCL-2 gene expression." (PMID 22134829, 2012). "Fas and Bcl2 families of genes are the best known among the factors that modulate cancer related apoptosis." (PMID 22458551, 2012). "In all the cancer cell lines analyzed, the simvastatin treatment appears to reduce anti-apoptotic BCL-2 expression and increase the transcription of Bax pro-apoptotic gene." (PMID 22134829, 2012). "Several natural compounds that have been shown to influence the Bax/Bcl-2 ratio in cancer cells are (−)-epigallocatechin-3-gallate (EGCG) and resveratrol." (PMID 22997533, 2012). "Inhibition of Bcl-2-mediated pathway by statins has also been shown by other labs in multiple cancer types." (PMID 22974127, 2012). "Bcl-2 is a well-known general apoptosis suppressor that induces the formation and development of carcinomas and suppresses apoptosis." (PMID 22654601, 2012). "MDA-7/IL-24 repressed Bcl-2 protein expression, which thus increased the ratio of specific pro- and anti-apoptotic proteins tilting the balance from survival to death in carcinoma cells." (PMID 22629368, 2012). "Released cytochrome c followed by Bcl-2 degradation promotes the caspase protease family activation, which mediates the intracellular proteolysis and finally induces carcinoma cell apoptosis." (PMID 22629368, 2012). "This article further focuses on compounds that have been studied the most and also discusses the anti-cancer potential of newer class of Bcl-2 drugs." (PMID 21760983, 2011). "Because Bcl-2 family members play a role in determining the sensitivity of cancer cells to gemcitabine, we examined the expressions of anti-apoptotic Bcl-2, Bcl-xL, and Bfl-1 by RT-PCR." (PMID 21843371, 2011). "These Bcl-2 proteins can essentially make cancer cells resistant to a variety of chemotherapeutic agents and therefore these proteins are currently important targets for the development of new anti-cancer agents." (PMID 21760983, 2011). "The constitutive activation of the STAT3 and Bcl-2 pathways is frequently observed in several cancer cell lines, including MM cells." (PMID 22177381, 2011). "A high Bax/Bcl-2 ratio was clearly correlated with increased apoptotic sensitivity to anti-cancer reagents." (PMID 21952498, 2011). "Previous reports have indicated that the anti-cancer effect of gossypol was due to its ability to interfere with the functions of Mcl-1, Bcl-2 and Bcl-xL (highest to lowest affinity) proteins." (PMID 21750559, 2011).